AFP (alpha fetoprotein)
Diseases named in the same sentence as AFP in open-access papers (continued):
Sharing a sentence is not in itself a finding about the gene and the disease.
tumor (continued). "Although targeting AFP therapy remains challenging due to tumor heterogeneity and drug resistance, the growing understanding of AFP-L3 and its prognostic value provides new directions for personalized treatment." (PMID 40458724, 2025). "The tumor marker cancer antigen 125 (CA125) was elevated at 131 U/ml, while other tumor markers, including alpha-fetoprotein (AFP), carcinoembryonic antigen (CEA), and CA199, remained within normal ranges." (PMID 40104406, 2025). "The GMScore was significantly correlated with tumor stage, histological grade, alpha-fetoprotein (AFP) levels, and vascular invasion, and a higher GMScore was identified as an independent risk factor for OS in both cohorts." (PMID 40361336, 2025). "Preoperative data, including routine blood tests and tumor markers (e.g., alpha-fetoprotein [AFP], carbohydrate antigen 19-9 [CA19-9], carcinoembryonic antigen [CEA]), were collected." (PMID 40128070, 2025). "Several risk factors have been shown to be correlated with recurrence, including vascular invasion, serum AFP level, tumor, size, and multiple lesions." (PMID 40186764, 2025). "MER demonstrated strong predictive ability for ER, with an AUC of 0.855, surpassing current indicators such as AFP, tumor size, and BCLC stage." (PMID 40075616, 2025). "In recent years, liver transplant eligibility criteria for HCC have evolved beyond the traditional Milan criteria, incorporating dynamic predictors, such as tumor biology, response to treatment, and non-invasive biomarkers, like AFP levels." (PMID 40566050, 2025). "A significant decline in serum AFP levels after surgery reflects the success of tumor removal, while improvements in LFTs underscore the recovery of hepatic health." (PMID 40206916, 2025). "The Barcelona Clinic Liver Cancer (BCLC) system is the most widely used subclassification method, primarily based on Child-Pugh grade of liver dysfunction, tumour size, and AFP levels." (PMID 40349011, 2025). "Higher levels of AFP, NLR, AAR, ALBI score, SII, and decreased CALLY index and N/CRP ratio were associated with increased pretreatment total tumor size, advanced BCLC stage, and out-of-UCSF criteria (P < .05)." (PMID 40181742, 2025). "Disease classification follows the pTNM system, ranging from stage IA to IIIC, with additional stratification based on tumor marker levels—namely of human chorionic gonadotropin (hCG), alpha-fetoprotein (AFP), and lactate dehydrogenase (LDH)." (PMID 40843751, 2025). "Serum tumor markers (alpha-fetoprotein (AFP), carcinoembryonic antigen (CEA), and carbohydrate antigen 19-9 (CA 19-9)) were found to be within normal parameters." (PMID 41230305, 2025). "Other than the imaging finding, AFP also serves as an important tumor marker in diagnosing and monitoring the response to treatment." (PMID 41001168, 2025). "The diagnostic efficacy of a single detection of tumor markers for HCC is limited; serum AFP, AFP-L3% and PIVKA-II still lack high sensitivity and specificity in the diagnosis of HCC." (PMID 40708828, 2025). "Postoperative serum AFP levels showed a significant decline, reflecting successful tumor resection and improvements in LFTs." (PMID 40206916, 2025). "The diagnostic process should begin with a pelvic ultrasound, followed by tumor marker assessment, including alpha-fetoprotein (AFP), beta-human chorionic gonadotropin (hCG), lactate dehydrogenase (LDH), and, if indicated, serum cancer antigen 125 (CA125)." (PMID 40310417, 2025). "Univariate analysis identified several factors associated with OS, including BW changes before and after treatment, Child-Pugh scores ≥ 8, ALBI grades 2 or 3, AFP levels ≥ 500 ng/mL, presence of infiltrative lesions, tumor size, and albumin levels." (PMID 41411278, 2025). "The French AFP model (AFP score) combines tumour number, largest diameter, and AFP level (0–9 points) to predict post-LT recurrence." (PMID 41301037, 2025).
tumor (continued). "The numbers of platelets and tumor markers (alpha-fetoprotein, carcinoembryonic antigen, and carbohydrate antigen 19-9) were all within the reference range." (PMID 40283372, 2025). "Diagnostic evaluation involves ultrasound, MRI, or CT for staging and tumor markers, such as alpha-fetoprotein (AFP), beta-human chorionic gonadotropin (β-hCG), and lactate dehydrogenase (LDH), to help differentiate histologic components." (PMID 40370888, 2025). "All tumor markers, including Alpha-Fetoprotein (AFP), Cancer Antigen 19–9 (CA19–9), and Carcinoembryonic Antigen (CEA) were normal." (PMID 40541022, 2025). "At maximal response, changes in CD90-positive circulating tumor cells reflected tumor burden more accurately than alpha-fetoprotein or des-gamma-carboxy prothrombin." (PMID 40940925, 2025). "HCC tumor factors were relatively matched between groups, including median AFP level, median number of tumors, largest tumor size, total number of locoregional treatments, and prior surgical resection." (PMID 40078822, 2025). "CCAT1-70aa was significantly upregulated in HCC tissues, correlating with tumor stage, serum alpha-fetoprotein levels, and vascular invasion." (PMID 40918165, 2025). "In recent years, PIVKA-II has also been utilized as an HCC tumor marker, complementing AFP to enhance HCC diagnosis and management." (PMID 40808940, 2025). "All the lab investigations were normal except for raised tumor markers like AFP and CA125, which subsequently decreased with the treatment." (PMID 41001168, 2025). "Our research suggests that the peptide CCAT1-70aa is significantly overexpressed in HCC, and its high expression is strongly correlated with tumor pathological staging, serum AFP concentration, and vascular invasion." (PMID 40918165, 2025). "In conclusion, we developed and validated an easily applicable score based on the baseline AFP level and initial tumor shape to predict the prognosis of HCC patients treated with ICIs." (PMID 39714631, 2025). "In vivo, bioluminescence imaging and serum alpha-fetoprotein (AFP) levels—strongly correlated with tumor burden (R2 = 0.92)—were used to monitor the response." (PMID 40722645, 2025). "For instance, earlier studies primarily focused on tumor recurrence or AFP reduction, whereas our analysis provided a more comprehensive evaluation of how Huaier affects both tumor biology and immune function across multiple dimensions." (PMID 40573279, 2025). "In the present case, the patient was febrile yet liver function tests and serum tumor markers alpha fetoprotein (AFP), carcinoembryonic antigen (CEA), and CA19-9 were all within normal limits." (PMID 41383505, 2025). "Laboratory analyses showed that tumor markers, including CA 19-9 (33 kU/L), alpha-fetoprotein (AFP), carcinoembryonic antigen (CEA), CA 125, and CA 72-4, were within reference ranges." (PMID 41517387, 2025). "In comparison, tumor size had a sensitivity of 73.7% and specificity of 57.1%, AFP demonstrated a sensitivity of 72.2% and specificity of 61.9%, while BCLC displayed a sensitivity of 61.1% and an impressive specificity of 90.5%." (PMID 40075616, 2025). "AFP is a biologically actionable molecule in HCC, as it has been implicated in tumor growth, angiogenesis, and immune modulation." (PMID 41002319, 2025). "All determined tumour markers (alpha-fetoprotein (AFP), carcinoembryonic antigen (CEA), CA 19-9, CA 125-II) were in the reference ranges." (PMID 40686398, 2025). "In multivariate analysis, GGT >104, AFP >200 μg/L, largest tumor diameter >5 cm, and lower MPV were found to be independent risk factors that affected the prognosis." (PMID 40091304, 2025). "The tumor marker alpha-fetoprotein (AFP) was 948.5 ng/ml (normal range ≤ 8 ng/ml), and the protein induced by the absence of vitamin K or antagonist-II (PIVKA-II) level was 387 mAU/ml (normal range ≤ 32.5 mAU/ml)." (PMID 40386774, 2025).
tumor (continued). "Univariate analysis of the Cox proportional hazards model showed that the factors significantly associated with OS and RFS were tumor size, tumor number, PVTT, TNM stage, CNLC stage, AFP level, and CD161 expression." (PMID 40115278, 2025). "Tumor-related factors, such as tumor size and protein induced by vitamin k absence or antagonist-II levels, were more favorable in the CSPH group, whereas AFP concentration, tumor differentiation, and microvascular invasion were comparable." (PMID 40739081, 2025). "They expand AFP-specific T cells, enhance interferon γ production, and elicit both class I and II tumor antigen responses." (PMID 41614820, 2025). "In a clinical setting, the frequently employed serum tumor markers for CRC encompass AFP, CEA, CA19-9, and CA72-4, among others." (PMID 38529374, 2024). "Currently, research on AFP has mainly focused on its role as a tumor/pregnancy marker and its cellular biological functions, whereas studies on the protein structure and properties of AFP have received less attention in recent years." (PMID 38678117, 2024). "The Variable Importance (VIMP) analysis revealed that the top five influential factors were tumor size, macrovascular invasion, microvascular invasion, tumor number, and AFP (Alpha-fetoprotein)." (PMID 39367397, 2024). "MT2 demonstrate that a combination of AFP and tumor burden parameters predicts post-LT outcome far betther than tumor alone." (PMID 40636728, 2024). "High circNUP54 expression is correlated with advanced TNM stage (AJCC classification), higher levels of alpha-fetoprotein (AFP), larger tumor size, and worse tumor differentiation." (PMID 38443362, 2024). "AFP, as a serum biomarker and tumor antigen, is the most widely accepted detection indicator in HCC." (PMID 38724499, 2024). "Tumor markers for liver lesions, including alpha-fetoprotein (AFP), carcinoembryonic antigen (CEA), and carbohydrate antigen 19-9 (CA19-9), were nonremarkable." (PMID 38686258, 2024). "One case report documented elevated tumor markers of AFP and PIVKA (34,748 ng/ml and 474 mAU/ml, respectively, with normal level CEA and CA19-9) in a patient with multiple liver nodules and a mass in the head of the pancreas with unclear origin." (PMID 38817451, 2024). "The study found that diosmin treatment significantly reduced the growth and size of HCC tumors and decreased the levels of various tumor markers, including alpha‐fetoprotein (AFP) and vascular endothelial growth factor (VEGF)." (PMID 39554345, 2024). "The tumor markers for alpha-fetoprotein (AFP), human chorionic gonadotropin (HCG), and lactate dehydrogenase were negative." (PMID 39238734, 2024). "One of the most common blood proteins in HCC is alpha-fetoprotein (AFP), a distinct tumor marker that is commonly used in HCC liver transplantation as well as HCC screening, diagnosis, treatment, and prognosis." (PMID 38998732, 2024). "For example, Metroticket Model was developed based on tumor size, tumor number and AFP level to predict HCC recurrence using a Cox-PH regression analysis." (PMID 38919938, 2024). "The effect was primarily seen in mice with small tumours and normal basal blood AFP levels, was attenuated by an anti-neuropilin-1 antibody, and depended on the concentration gradient between tumour and blood." (PMID 38889481, 2024). "Due to the complexity of tumor components, AFP and β-hCG levels in the NGGCT showed significant variability." (PMID 39737398, 2024). "We established an IFP based on three inflammatory biomarkers (IL6, osteocalcin, SII) and a tumor marker AFP." (PMID 39188937, 2024). "AFP promotes the formation of an immune-tolerant microenvironment and facilitates immune evasion of tumor cells." (PMID 38660138, 2024). "We included measures such as tumor characteristics (baseline tumor size, AFP level, and vascular invasion), serum bilirubin levels, blood-clotting parameters, and other liver function indicators." (PMID 38660298, 2024).
tumor (continued). "The rate of complete elimination of tumor tissue was 100% and the AFP level was returned to normal within 3 months after surgery in both groups (P > 0.05)." (PMID 38715071, 2024). "This correlation between agrin and AFP further underscores the complexity of the tumor microenvironment and its impact on biomarker expression." (PMID 39123447, 2024). "AFP-L3, a glycoform of AFP that specifically binds to lens culinaris agglutinin, has emerged as a novel tumor marker for HCC19." (PMID 38678117, 2024). "Widely available monitoring tests include tumor markers such as alpha fetoprotein (AFP) as well as various imaging techniques including ultrasound (US), computed tomography (CT), and abdominal magnetic resonance imaging (MRI)." (PMID 38817899, 2024). "AFP level ≤ 400 μg/L, tumor numbers one to three, presence of metastasis, and receiving the HAICCR triple therapy regimen were found to be prognostic factors associated with PFS." (PMID 38717693, 2024). "Tumor markers such as AFP, CEA, CA1-99, PIVKA-II, and CA7-24 are more normal, and their negative results help distinguish them from other tumors in the liver." (PMID 38807765, 2024). "At 32 weeks of gestation, a follow-up ultrasound revealed a significant increase in tumor size compared with the previous observation, with an increase in AFP levels." (PMID 39309737, 2024). "The proportion of MVI‐positive patients with hepatocirrhosis, AFP‐positive, tumor diameter >50 mm, and LMR ≤3.4 was significantly higher than that of MVI‐negative patients." (PMID 38284881, 2024). "Laboratory results revealed significantly elevated tumor markers, with alpha-fetoprotein (AFP) levels of 737.9 ng/mL (reference <8.8 ng/mL) and a beta-human chorionic gonadotropin (β-HCG) level of 692 IU/L (reference 0-3 IU/L)." (PMID 39677122, 2024). "In the univariable analysis, several factors were significantly associated with OS, including age, etiology, largest tumor size, tumor number, AFP level, and ALBI grade." (PMID 38606106, 2024). "Worse overall survival among HCC-bone metastasis patients was associated with Child–Pugh class A group, alpha-fetoprotein (AFP) levels over 30 ng/mL, a tumor size greater than 5 cm, and skeletal-related events." (PMID 39682684, 2024). "The LAUNCH study, employing univariate and multivariate analyses, indicated that tumor number, microvascular invasion (MVI), and AFP level are risk factors for PFS." (PMID 39035736, 2024). "In this study, AFPGC is characterized by serum AFP exceeding the normal upper limit, obviating the need for AFP immunohistochemistry in tumor tissues." (PMID 39902132, 2024). "Serum AFP levels have been described as the tumor characteristic most strongly predictive of post-transplant survival." (PMID 38672535, 2024). "HCC patients with higher levels of blood tumor markers (AFP, AFP-L3) have a higher expression of DLK1, along with simultaneous co-expression with other HPC markers." (PMID 39769389, 2024). "Subsequently, these CAR T cells degranulated, secreted various cytokines and lysed HLA-A02:01+/AFP+ tumor cells." (PMID 38473878, 2024). "Only a few cases were detected through elevated serum tumor markers, such as AFP (45.05%), CEA (5.68%), and CA19-9 (29.21%)." (PMID 39867929, 2024). "Patients were selected on the basis of tumour biology markers such as AFP levels, tumour differentiation, response to bridging therapy and the presence of cancer-related symptoms." (PMID 38473282, 2024). "Some recent prognostic scores, such as the CLIP score and the ITA.LI.CA score, also include serum AFP, in addition to other clinical and tumor features." (PMID 38792876, 2024). "Building on these prior findings, our study investigated the relationship between early AFP response and early tumor progression in patients undergoing ICI combined with targeted therapy." (PMID 39767676, 2024).
tumor (continued). "The new TP score consists of tumor size and number, AFP level, and ALBI grade, with the latter two factors newly incorporated into the 2022 BCLC staging system to stratify HCC patients." (PMID 38606106, 2024). "The findings revealed that the proportion of hepatocirrhosis, AFP levels, and tumor diameter were higher in MVI‐positive patients than in MVI‐negative patients, although the LMR was lower in MVI‐positive patients than in MVI‐negative patients." (PMID 38284881, 2024). "The diagnostic model and nomogram were constructed to estimate the incidence of early TACE refractoriness based on tumor size, bilobular invasion, AFP, and APRI." (PMID 39258671, 2024). "AFP is a widely used tumor biomarker in the clinical practice and is considered as a positive predictor for the recurrence and the progression of HCC." (PMID 38365678, 2024). "Serum tumor markers were significantly elevated, with AFP and HCG levels suggesting the presence of an NSGCT." (PMID 39697937, 2024). "Changes in the AFP-DCP expression patterns were delineated based on variations in the number of positive tumor markers when comparing pre- and post-operative patterns." (PMID 38903723, 2024). "Changes in tumor markers (alpha-fetoprotein [AFP] and des-gamma-carboxy prothrombin [DCP]) from baseline to 4 weeks after treatment (ΔAFP/ΔDCP) were included as the input factors." (PMID 39321197, 2024). "The nomogram, including age, tumor number, tumor size, γ-GT, and PT, demonstrates better predictive ability for AFP-NHCC patients with DCP positive." (PMID 39175473, 2024). "Evaluation should take into consideration a complete blood count, physical examination including gynecological exam, tumor markers (CA‐125, CA 19‐9, AFP), mammography and breast ultrasound, and a thoraco‐abdomino‐pelvic CT scan." (PMID 39224678, 2024). "Tumor size, T stage, N stage, AFP level, fibrosis score and grade were proved as independent prognostic factors of HCC patients." (PMID 37067674, 2024). "Skeletal muscle loss, serum AFP, and CRP levels have been identified as potential predictors of overall survival and tumor response in unresectable HCC patients undergoing the combination of TKIs and PD-1 inhibitors." (PMID 38698848, 2024). "Serum tumor markers were elevated: α-fetoprotein (AFP) = 833.1ng/ml, CA125 = 422.1U/ml, CA19−9 = 81.81U/ml, β-human chorionic gonadotropin (HCG) was negative.During the surgical exploration, a significant amount of yellow ascites was observed." (PMID 39077470, 2024). "The results showed that, compared to cluster A, cluster B has the following characteristics: poorer tumor differentiation, more advanced stage, younger age, more female patients, more prone to vascular invasion and higher serum AFP levels." (PMID 39323867, 2024). "AFP secretion in HCC results from a re-expression of a fetal antigen in the tumor, and PIVKA-II results from an independently acquired posttranslational defect in protein processing." (PMID 38622445, 2024). "The data of the present study indicate that iRGD induced a tumour-blood transport as detected by a rapid elevation of the blood AFP level in mice with HCC." (PMID 38889481, 2024). "The blood workup showed three elevated serum tumor markers, AFP at 2643 μg/L (normal < 8 μg/L), CA-125 at 145 U/mL (normal < 30 U/mL), and CA-19-9 at 113 U/mL (normal < 31 U/mL); the serum tumor marker hCG was normal at 2 mIU/mL (normal < 10 mIU/mL)." (PMID 39734342, 2024). "Alpha-fetoprotein (AFP) is a conventional tumor marker for predicting HCC recurrence, but its sensitivity is relatively low." (PMID 38476367, 2024). "It is noteworthy that the correlation of AFP, incomplete tumor capsule and I-O and MTT and overall survival after hepatectomy for HCC with PVTT has been established." (PMID 39170098, 2024). "Regarding tumour characteristics, sarcopenic recipients had higher preoperative AFP (P = 0.006), tumour size (P = 0.003), and tumour number (P = 0.022) than non‐sarcopenic recipients." (PMID 39192518, 2024).